ATRX (ATRX chromatin remodeler)
Diseases named in the same sentence as ATRX in open-access papers (continued):
Sharing a sentence is not in itself a finding about the gene and the disease.
tumor (continued). "Others use less-strict cutoffs, for example, <10, <15%, or even <50% of tumor nuclei that stain for ATRX." (PMID 34458259, 2021). "Thirdly, important molecular characteristic data including TERT, 1p/19q LOH and ATRX were unobtainable because of tumor tissue status." (PMID 33596518, 2021). "NPC patients with ATRX expression, defined as ATRX positive staining in at least 1% of nuclei in the tumor cells, consist of 76.7% (174/227) of the cohort." (PMID 34729095, 2021). "The withdrawal B (from a manual macrodissection) had a Ki-67 LI = 36% and pTERT wild type tumour cells with retained ATRX expression." (PMID 34573966, 2021). "Tumor-infiltrating monocytic-lineage cells from ATRX KOs expressed less class II HLA and higher levels of Arg1, Vegfa, and other markers of the immunosuppressive M2 phenotype." (PMID 34763709, 2021). "PDX1 had lower expression and hypermethylation in ATRX/DAXX/MEN1 mutant tumours (T2 and T3) than wild-type tumours (T1)." (PMID 33536587, 2021). "Overall, the prevalence of ATRX alterations in LPS are about 20% and increase with tumor de-differentiation (n = 203)." (PMID 34069193, 2021). "Patients with ACC showing high ATRX expression, defined as tumor scored 2+ or higher, represented 47.5% of cohort." (PMID 33513905, 2021). "An important role of ATRX and telomere maintenance mechanisms during tumor progression was also confirmed by the presence of alternative lengthening of telomeres (ALT) in ATRX-mutated metastasizing PPGLs." (PMID 34833055, 2021). "Nevertheless, inducing tumor differentiation in ATRX- or DAXX-null ALT+ OS is a fascinating idea with potential therapeutic implications worth further inquiry." (PMID 34069193, 2021). "The performance evaluation of the proposed work indicates that linking simple, clinically feasible radiomics (i.e., tumor volumetric features) to RNAseq improves the performance of IDH and ATRX mutations prediction." (PMID 34490297, 2021). "Whole exome sequencing of non-familial pNETs revealed inactivating-to-missense mutations in either ATRX or DAXX in up to 65% of tumors, predicting tumor suppressive roles in pNET pathogenesis." (PMID 34680266, 2021). "ATRX/DAXX mutation and the ALT phenotype also correlated with increased chromosomal instability, advanced tumor stage and metastasis, and reduced relapse-free survival." (PMID 34680266, 2021). "The results indicated that age, tumor grade, IDH mutation, ATRX mutation, MGMT methylation, and immune score were significantly associated with OS (p < 0.001)." (PMID 34721530, 2021). "In malignant tumours, all but two cases (80/82, 97.6%) showed a diffuse nuclear immunoreactivity for ATRX in tumour cells." (PMID 34573966, 2021). "Several authors have extensively demonstrated the expression of GBM markers, such as EGFR, MGMT, IDH1 R132H, and ATRX, in tumor cells using IHC, which is much more applicable for neuropathology routine." (PMID 33673104, 2021). "In total, 64 tumor samples had truncating ATRX (n = 53) or DAXX alterations (n = 11), and are referred to as ATRX/DAXXtrunc in the following analysis." (PMID 32024817, 2020).
tumor (continued). "After adjustment for WHO grade, ATRX, Ki67 and TERT, the molecular groups of IDH1 and MGMT were independently associated with tumor growth." (PMID 32388499, 2020). "All patients had neuropathologically confirmed GBM with an expression of wild-type isocitrate dehydrogenase 1 (IDH-1) and wild-type ATRX and underwent resection of their tumor with 5-ALA guidance." (PMID 32904996, 2020). "Our analysis of ATRX-status prediction shows that tumor information measure of correlation imaging feature and histogram mean tumor volume are the most frequently selected features." (PMID 32111869, 2020). "In the representative sample of 2409, ATRX-positive cells were persistent in the mouse while the ATRX-positive tumor cells in the parental tumor were diffuse." (PMID 32698368, 2020). "On average, telomere content was gained in ATRX/DAXXtrunc (mean telomere content tumor/control log2 ratio = 0.3), while telomere sequences were lost in TERTmod samples (mean telomere content tumor/control log2 ratio = −0.4)." (PMID 32024817, 2020). "Western blot assay was used to detect the expression of ATRX protein in tumor tissues and the biomarkers of proliferation and apoptosis." (PMID 33194637, 2020). "ATRX/DAXX loss occurs in 18 and 25% of PanNETs and leads to ALT phenomenon, chromosomal instability and higher tumor stage suggesting this mutation is a late event in the neoplastic transformation." (PMID 32537434, 2020). "After adjusting for WHO grade, ATRX, Ki67, and MGMT, the IDH1, TERT, and 1p/19q molecular groups were independently associated with tumor growth." (PMID 32388499, 2020). "Tissue sections from successful PDX models were stained with IDH1R132H, Ki67 and ATRX to confirm molecular similarities with parental tumor." (PMID 32698368, 2020). "Of genes previously reported as commonly mutated in PNETs, only PDGFRA and MTOR were found to be mutated in a few tumor samples, and other genes, including ATM, ATRX, TSC2, DAXX, VHL, and MEN1, were mutated only in individual samples." (PMID 32586046, 2020). "The information content of correlation and the histogram mean of the tumor volume of the most frequently selected features are employed in the XGBoost model to train and predict ATRX status." (PMID 32111869, 2020). "We also found evidence for increased telomere length (tumor:normal ratio) in the majority of samples and disruption in either ATRX or DAXX or in the TERT promoter." (PMID 30889380, 2019). "ATRX is a tumor suppressor gene located on chromosome X and biallelic inactivation of this gene through mutations or chromosome X inactivation is associated with tumorigenesis in a variety of tumors." (PMID 31856217, 2019). "Since then, mutations in both ATRX and DAXX have been found in a variety of different tumor types and seem to be especially prevalent in tumors associated with the central nervous system." (PMID 29479426, 2018).
tumor (continued). "Consistent with this, mutations in the genes encoding ATRX (involved in telomere maintenance) and in the promoter region of telomerase itself (TERT) have been reported in SDH-deficient tumours." (PMID 29450727, 2018). "ATRX inactivating mutations are intrinsically linked to ALT in CNS tumours and other tumour histotypes (e.g., pNETs)." (PMID 29751586, 2018). "The majority of mutations in ATRX, DAXX, and MEN1 were truncation mutations (stopgain or frameshift) and loss of function consistent with their role as tumor suppressors." (PMID 30315258, 2018). "Genotyping revealed that the majority of the primary tumor variants were identified in MEN1 (42.2%), DAXX (11.1%), ATRX (10%), and TSC2 (7.8%) genes." (PMID 29212165, 2017). "The most prevalent primary tumor variants were in the MEN1 (42%), DAXX (11%), ATRX (10%), and TSC2 (8%) genes." (PMID 29212165, 2017). "Previous studies on these gene alterations, especially those of TERTp and the ATRX gene, have mostly focused on primary tumours, with little investigation of paired recurrent tumours." (PMID 29026176, 2017). "ATRX and MLL3 (also known as KMT2C) were mutated in all regions in C3 except regions originating from tumour sample S2." (PMID 28916750, 2017). "We did not observed any correlation between SSAs-induced cell viability inhibition and the presence of MEN1 tumor mutations or PTEN, DAXX/ATRX expression levels." (PMID 28454119, 2017). "In the “waves” pattern CESC, the first wave genes EP300, MLL2, and MLL3 were all tumor suppressor genes, and the second wave genes FBXW7 and ATRX were also tumor suppressor genes." (PMID 26992457, 2016). "In patient 3, double staining with anti-ATRX and anti-IDH1 R132H antibodies identified: (i) areas with maintained ATRX expression in tumor cells, and (ii) areas with diffuse loss of ATRX expression in tumors cells." (PMID 27036230, 2016). "Although it has been proposed that ATRX is a tumour suppressor, the role of ATRX in ALT has remained unclear." (PMID 26143912, 2015). "Mutations in members of the ATRX/DAXX chromatin remodeling complex have been implicated in the ALT mechanism, in both ALT-positive cell lines and tumor samples." (PMID 26001292, 2015). "Among the genes that are mutated between 5 to 20% in TCGA GBM tumor samples, we found mutations in NF1, SPTA1, TCHH and ATRX genes, although, the other genes like PIK3R1, PIK3CA, RB1, IDH1 and KEL were not mutated in any cell line." (PMID 26496030, 2015). "For comparison, we also show the TARGET Project's initial analysis, which reported 16 multi-exon deletions within ATRX by comparing tumor to matched normal samples." (PMID 25618849, 2015). "Nonetheless, APBs were markedly reduced following transient transfection of the ATRX cDNA for 48 h, strongly suggesting that ATRX functions as a tumour suppressor in other ALT cancers." (PMID 26143912, 2015). "Using genomic PCR with a pair of primers flanking this deleted region, we experimentally verified the ATRX deletion in all three tumor samples." (PMID 24147068, 2013).
tumor (continued). "Tumour specimens were stained with multiplex immunofluorescence, and a pathologist selected regions of interest (ROIs), which were scanned at high magnification and analyzed with markers including ATRX, CD8, STING, DAPI, CD4, CD11c and TCRγ/δ." (PMID 39856469, 2025). "Thus, the role of DAXX and ATRX in tumour biology must always be interpreted within the specific tumour type, both in human and veterinary oncology." (PMID 41472189, 2025). "Notably, the primary tumor clustering with α-lineage PanNETs showed ATRX retention, while the matching metastasis clustered with the ADM tumors and was ATRX negative." (PMID 41212394, 2025). "Although no direct evidence links ATRX mutations to M1/M2 macrophage polarization or function, mast cells are known to interact closely with macrophages in the tumor microenvironment." (PMID 40495762, 2025). "In a minority of cases, tumours exhibit loss of DAXX (a binding partner of ATRX) and, more rarely still, ALT-like processes operate in tumours with neither ATRX nor DAXX loss." (PMID 39921567, 2025). "Our findings suggest that targeting tumours with loss of expression for DAXX and/or ATRX may be of particular interest for treating highly aggressive UC in veterinary oncology." (PMID 41472189, 2025). "To explore which transcription factors may be driving changes in transcriptional programming in TERT and ATRX altered tumours we performed binding motif enrichment analysis using single-nuclei ATAC-sequencing." (PMID 40097403, 2025). "In line with this evidence of the co-dependency between ATRX and H3.3G34R, studies using mouse models of DHG showed that the overexpression of H3.3G34R leads to the enrichment of neuronal markers in the tumours, the cell of origin of DHGs, only when ATRX is lost." (PMID 40986124, 2025). "Alterations in the expression of DAXX and/or ATRX can influence tumour biology." (PMID 41472189, 2025). "Desirable criteria are MAPK pathway gene alterations and homozygous deletion or mutation of CDKN2A and/or CDKN2B (both present in this tumour), as well as mutation of ATRX and anaplastic histological features (both not present in this tumour)." (PMID 39427038, 2024). "High-grade astrocytoma with piloid features (HGAP) is a distinct tumour type but has morphological overlap with pilocytic astrocytoma and also typically carries a variant driver in the MAPK pathways (often with additional variants in ATRX and/or CDKN2A/B)." (PMID 39294363, 2024). "Likewise, specificity was lower for ATRX-retained tumor tissue compared to ce-T1 (0.78 vs. 0.8), but sensitivity was much higher (0.74 vs. 0.42)." (PMID 39061219, 2024). "Also, it is suggested that the expression level of tumor-associated genes, such as IDH-1, ATRX, and NLGN3, was correlated with several cognitive domains." (PMID 38315329, 2024). "One method of measuring ALT-positivity is determining the incidence of ATRX or DAXX mutations, which are prevalent in ALT-positive tumours and therefore may be considered proxy markers of potential sensitivity to ATR inhibition." (PMID 38287179, 2024). "The median tumor volume was approximately equal in both ATRX wild-type and mutant cases." (PMID 39684754, 2024).
tumor (continued). "ATRX gene mutations lead to the loss of nuclear protein expression in tumor cells while preserving expression in non-tumor cells like endothelial and pre-existing glial cells, which act as a positive internal control." (PMID 39767571, 2024). "The exome profiles of both corticotroph PitNET showed an ATRX gene variant that has been previously related to tumor susceptibility although, it has not been related to corticotroph PitNET previously." (PMID 39217365, 2024). "High-risk neuroblastoma tumours frequently suffer from TERT rearrangement and ATRX inactivation." (PMID 39715281, 2024). "Likewise, tumor tissue with retained ATRX showed significantly higher TBRs compared to tumor tissue with ATRX loss (p < 0.010)." (PMID 39061219, 2024). "This is particularly relevant in the case of PNET because PNETs have a low tumor mutational burden and are considered an epigenetic disorder due to the fact that multiple high-frequency mutations, including MEN1, DAXX, and ATRX, are all found involved in epigenetic regulation." (PMID 38279330, 2024). "However, TBR was acceptable for classifying ATRX-retained tumor tissue (AUC = 0.78, 95% CI: 0.63–0.93) and excellent for classifying IDH1-wildtype tumor tissue (AUC = 0.83, 96% CI: 0.7–0.95)." (PMID 39061219, 2024). "More recently, the role of ATRX in tumor suppression has been described." (PMID 39351526, 2024). "Combined models with a greater range of tumor-related data might show better performances (eg, Ki67 percentage, ATRX status, genomic variables)." (PMID 38285679, 2024). "Mutations in TERT (telomerase reverse transcriptase promoter) and ATRX may allow tumor cells to escape apoptosis." (PMID 38674026, 2024). "However, the role of ATRX in tumor development and response to cancer therapies remains poorly understood." (PMID 37200088, 2023). "ATRX deficiency impairs non‐homologous end joining (NHEJ) by hindering the recruitment of pDNA‐PKcs, potentially through conformational changes in heterochromatin, leading to genetically unstable tumors and aggressive tumor behavior." (PMID 37311690, 2023). "Similarly, the loss of ATRX/DAXX immunohistochemical expression was identified in 18/46 cases of PanNET tumors and was correlated with tumor size larger than 5 cm." (PMID 37958340, 2023). "The aim of this study was to assess whether different ATRX aberrations are molecularly distinct from one another and how they might contribute to tumor development." (PMID 37540673, 2023). "Gene set enrichment analysis (GSEA) showed decreased expression of genes related to both ribosome biogenesis and several metabolic processes in our isogenic ATRX exon 2–10 MED model systems, the patient-derived MED models and in tumor data containing two patients with an ATRX exon 2–10 MED." (PMID 37540673, 2023). "The contribution of ATRX loss to tumor development and treatment response is not well defined, despite mutations in ATRX occurring in approximately 6% of all human cancers." (PMID 37200088, 2023). "Nevertheless, more research in additional tumor types is needed to confirm whether this is a universal phenomenon in ATRX KO cells." (PMID 37540673, 2023). "ATRX together with DAXX encode a complex that deposits the histone variant H3.3 into repetitive heterochromatin, including retrotransposons, pericentric heterochromatin, and telomeres, the latter of which show deregulation in ATRX/DAXX-mutant tumours." (PMID 35975235, 2022).